CIB1 (calcium and integrin binding 1)
Diseases named in the same sentence as CIB1 in open-access papers (continued):
Sharing a sentence is not in itself a finding about the gene and the disease.
infection (9 papers, 2013 to 2020). The state of being infected such as from the introduction of a foreign agent such as serum, vaccine, antigenic substance or organism. "Infection increased the association of CIB1 with LRs, and CIB1 was associated with EphA2 and KSHV entry associated signal molecules such as Src, PI3-K, and c-Cbl." (PMID 24550731, 2014). "Splicing is induced during infection, resulting in the expression of a Cib1 variant containing a functionally important Clp1 interaction domain." (PMID 24146612, 2013). "Since our results demonstrated that infection also induced the enhanced association of CIB1 with LRs of infected cells and CIB1 plays a role in macropinocytosis, we rationalized that CIB1 might interact with LR associated KSHV entry receptors especially EphA2 early during infection." (PMID 24550731, 2014). "Consistent with the results obtained in infection studies, PUMAG_12184‐driven expression of cib1 resulted in increased expression of PR3 and PR5 genes at 2 dpi, whereas expression of PR1 was not induced." (PMID 31802604, 2020). "Whole cell expression levels of TRAIL-R2 also increased with CIB1 depletion starting at Day 2, but more significantly at Day 3 post-infection." (PMID 30740034, 2019). "Overall, our studies identify CIB1 as a host factor regulating a virus primary infection as well as endocytosis for the first time." (PMID 24550731, 2014). "Progression toward infection is regulated by several bE/bW-induced factors, including Clp1 and Cib1." (PMID 24146612, 2013). "Specificities of these associations were demonstrated by their significant reduction, ∼77%, 100%, and 95%, respectively, in CIB1 knockdown cells as well as by ∼50%, 72%, and 40%, respectively, in infection with heparin-treated KSHV (lanes 4 and 5 in panels b, c and d)." (PMID 24550731, 2014). "Interestingly, the CIB1 staining pattern was also coherent with flotillin-1 as both the molecules were more clustered with infection, compared to a diffused pattern in the uninfected HMVEC-d cells." (PMID 24550731, 2014). "CIB1 knockdown significantly reduced the infection induced EphA2, Src and Erk1/2 activation." (PMID 24550731, 2014). "To determine the mechanism by which CIB1 plays a role in KSHV entry and infection, we next determined whether CIB1 associates simultaneously with components of the EphA2 assembled multi-molecular signal complex such as Src, PI3-K, and c-Cbl." (PMID 24550731, 2014). "FACS analysis of cell surface expression of b) TRAIL-R1 and c) TRAIL-R2 in CIB1 depleted (shCIB1) MDA-436-PR and MDA-436-DCXR cells normalized to IgG-stained control cells (shCTRL) 4 days post infection with RNA interference." (PMID 30740034, 2019). "Elucidation of the mechanisms through which CIB1 and CIB2 promote infection is likely to provide new insights into the strategies used by HIV-1 to co-opt normal cell functions to efficiently transfer capsids into the cytosol." (PMID 27489023, 2016). "Reducing the expression of both CIB1 and CIB2 also significantly decreased productive infection efficiency measured at 24 h, showing that CIB1 and CIB2 are required for both cell-free and cell-to-cell virus transmission." (PMID 27489023, 2016). "The percentage of cells expressing intracellular Gag at day 3 post-infection with HIV-1NL4-3 was decreased by 70% and 60%, respectively, following down modulation of CIB1 and CIB2." (PMID 27489023, 2016). "Together, these studies reveal for the first time the role of CIB1 as a potential adaptor molecule in virus macropinocytic entry and indicate CIB1 as an attractive target to block KSHV entry and infection." (PMID 24550731, 2014). "Both ICP0 and ICP4 transcript levels in CIB1-shRNA HMVEC-d cells were unchanged compared to sh-control HMVEC-d cells indicating that CIB1 is specifically involved in KSHV entry and primary infection." (PMID 24550731, 2014).
infection (continued). "More importantly, knocking down CIB1 significantly inhibited KSHV entry and de novo infection due to a substantial reduction in EphA2 induced signal amplification." (PMID 24550731, 2014). "Together, these studies reveal for the first time the role of CIB1 as a potential adaptor molecule in virus macropinocytic entry and promote CIB1 as an attractive target to block KSHV entry and infection." (PMID 25341665, 2014). "CIB1 knockdown studies demonstrate significant reduction in KSHV-induced bleb formation, activation of EphA2, Src, and Erk1/2, virus entry by macropinocytosis, productive trafficking, and infection." (PMID 25341665, 2014). "CIB1 depletion by shRNA significantly reduced KSHV-induced bleb formation, activation of EphA2, Src, and Erk1/2, virus entry by macropinocytosis, productive trafficking, and infection." (PMID 24550731, 2014). "By conditional expression of the central UPR regulator, Cib1, in U. maydis, we show that a functional UPR is required for continuous plant defence suppression after host infection and that U. maydis relies on a robust control system to prevent deleterious UPR hyperactivation." (PMID 31802604, 2020). "Since we observed that CIB1-shRNA significantly inhibited KSHV infection in HMVEC-d cells, we tested whether CIB1 colocalized with KSHV in virus induced membrane bleb protrusions early during infection." (PMID 24550731, 2014). "We found that TRAIL-R2, but not TRAIL-R1, was upregulated on the surface of CIB1-depleted versus control MDA-436 TNBC cells, starting 2 days post-infection with both CIB1-1 and CIB1-2 shRNA sequences." (PMID 30740034, 2019).
CIB1 also shares sentences with these, for which no sentence is quoted: cardiac hypertrophy (2 papers); breast tumor (1); cardiac insufficiency (1); colorectal adenocarcinoma (1); colorectal cancer (1); gastric cancer (1); genetic diseases (1); glioma (1); hepatocellular carcinoma (1); influenza infection (1); Kaposi's sarcoma (1); leiomyosarcoma (1); liver cancer (1); metabolic syndrome (1); Myocardial fibrosis (1); myocardial infarction (1); oculocerebrorenal syndrome of Lowe (1); ovary tumour (1); papillary renal cell carcinoma (1); Stroke (1); valvular heart disease (1); Wiskott-Aldrich syndrome (1).